IL33 (interleukin 33)
Diseases named in the same sentence as IL33 in open-access papers (continued):
Sharing a sentence is not in itself a finding about the gene and the disease.
atherosclerosis (continued). "The role of IL-33 has been reported in atherosclerosis, but the precise mechanism is not known, particularly its effect on neutrophil and macrophage function." (PMID 36552551, 2022). "Nevertheless, plaque stability from the treated and untreated group remained unchanged, characterized by similar VSMC and collagen content, suggesting that IL-33 treatment decreases atherosclerosis plaque size without affecting plaque stability." (PMID 35600479, 2022). "In conclusion, research on IL-33 and its multiple controversial effects on atherosclerosis are not yet fully elucidated and need to be better understood." (PMID 35600479, 2022). "Thus, IL-33/ST2L induces polarization of the anterior atherosclerotic immune response from the Th1 to the Th2 type and inhibits atherosclerosis progression." (PMID 36337880, 2022). "Recently, there was reported an involvement of the IL-33/ST2 axis in the generation of Th17 cells and the production of IL-31 and that the IL33/IL-31 axis is a link between osteoporosis and accelerated atherosclerosis in psoriatic arthritis." (PMID 31973226, 2020). "Furthermore, the expression of IL-33 and its receptor ST2 in murine and human cells and tissue reduces atherosclerosis development in ApoE-/-mice." (PMID 27223112, 2016). "In contrast, in a recent study, deficiency of IL-33 and ST2 did not affect development of atherosclerosis in ApoE-deficient mice." (PMID 27142573, 2016). "Consistently, LDL, a critical lipid for the development of atherosclerosis, was in negative correlation with IL-33 (r = −0.33, p = 0.03)." (PMID 27579324, 2016). "The objective of our study was to examine the role of endogenous IL‐33 and ST2 in atherosclerosis." (PMID 26417439, 2015). "In summary, deficiency of the endogenously produced IL‐33 and its receptor ST2 does not impact the development of atherosclerosis in ApoE‐deficient mice." (PMID 26417439, 2015). "Although IL-33 and ST2 play a role in the pathogenesis of atherosclerosis, circulating sST2 is neither associated with carotid plaque morphology nor with symptomatic cerebrovascular events, i.e., TIA and stroke, in patients with high-grade carotid artery stenosis." (PMID 37240352, 2023). "However, there are also studies showing that atherosclerosis severity was not affected by IL-33/ST2 signaling." (PMID 35600479, 2022). "Further, the role of IL-33 in NET induction in advanced atherosclerosis is also not understood." (PMID 36552551, 2022). "However, the precise mechanism of action of IL-33 in regulating neutrophil and macrophage functioning is not defined in advanced atherosclerosis (aAT) patients." (PMID 36552551, 2022). "However, the knockout of ST2 or IL-33 showed no beneficial effect on atherosclerosis development in ApoE−/− mice." (PMID 33415128, 2020). "The present study demonstrates that IL-33 induces IL-8 expression via JNK/c-Jun/AP-1 pathway in human vascular endothelial cells, and provides a new insight into the role of IL-33-induced IL-8 in the pathophysiology of atherosclerosis and vascular inflammation." (PMID 29373608, 2018). "However, IL33 and IL-25 activate may other cellular responses independently of ILC2, and type II cytokines are also secreted by other cell types and may act on atherosclerosis independently of ILC2." (PMID 28589929, 2017). "In the same way, it was reported that deficiency of the endogenously produced IL-33 and its receptor ST2 did not impact the development of atherosclerosis in ApoE-deficient mice while the administration of exogenous IL-33 reduces the development of atherosclerosis." (PMID 28611297, 2017). "While IL-33 exacerbates autoimmune collagen-induced arthritis via mast cell degranulation 22, it also promotes type 2 immune responses with the production of high levels of IL-5 and IL-13 20 and drives M2 macrophage differentiation thus protecting mice from EAE 26 and atherosclerosis." (PMID 25116404, 2014).
atherosclerosis (continued). "However, the role of IL-33 in the pathophysiology of atherosclerosis is not fully understood yet." (PMID 29373608, 2018). "On the contrary, ST2 and IL-33 have been found in human atherosclerotic tissues where they stimulated the production of adhesion molecules and chemokines, although a preclinical study found no role of ST2/IL-33 in the development of atherosclerosis in ApoE−/− mice." (PMID 41163220, 2025).
autoimmune disease (86 papers, 2010 to 2025). A disorder resulting from loss of function or tissue destruction of an organ or multiple organs, arising from humoral or cellular immune responses of the individual to their own tissue constituents. "Epithelium-derived cytokines, such as IL-33, IL-25, and thymic stromal lymphopoietin are alarmins that are involved with type-2, type-1, and type-17 immune responses, and are associated with autoimmune diseases and allergic disorders." (PMID 39214920, 2024). "These responses culminate in the production of a plethora of cytokines such as TSLP, IL-9, IL-25, and IL-33, which have been implicated in the pathogenesis of several inflammatory and autoimmune diseases." (PMID 37063828, 2023). "Plasma interleukin-33 (IL-33), a cytokine associated with inflammatory and autoimmune disease, has been described to be significantly raised in osteonecrosis of the femoral head (ONFH) and hence was recommended for use as a marker for ONFH." (PMID 35371856, 2022). "With their expression by barrier epithelial cells, the cytokines interleukin-25 (IL-25) and IL-33 play key roles in intestinal immune responses, and have been associated with inappropriate allergic reactions, autoimmune diseases and cancer pathology." (PMID 36263033, 2022). "The role of IL-33 has been underlined in several inflammatory and autoimmune diseases including systemic lupus erythematosus (SLE)." (PMID 35328556, 2022). "Interleukin-33 (IL-33), a member of the IL-1 cytokine family, has been recently associated with the development of autoimmune diseases, including systemic lupus erythematosus (SLE)." (PMID 33182616, 2020). "Previously, several articles unraveled the correlation between IL-33 gene polymorphisms and autoimmune diseases, such as ankylosing spondylitis, Behçet's disease, and lupus, and these studies all presented strong susceptibility." (PMID 30984790, 2019). "IL-33/ST2 overstimulation has been implicated in airway inflammatory diseases, autoimmune diseases, viral infection diseases, and many other diseases, suggesting an important role for IL-33/ST2 in the development of inflammatory pathologies." (PMID 25658420, 2015). "Through binding to the orphan receptor ST2, IL-33 can induce gene expression of Th2-associated cytokines, promote Th2 type immune response, and thus play important roles in autoimmune diseases." (PMID 26675669, 2015). "ST2 deletion and exclusion of IL-33/ST2 axis are accompanied by enhanced susceptibility to dominantly T cell-mediated organ-specific autoimmune diseases." (PMID 25032216, 2014). "Interleukin-33 (IL-33), a novel member of IL-1 family, has been recently implicated in several inflammatory and autoimmune diseases." (PMID 24151520, 2013). "IL-33/ST2 signaling is also implicated in autoimmune disease and in an experimental animal model of diabetes I induction by multiple doses of streptozotocin this pathway seems to exert a protective effect possible through balancing Th1/Th2 response." (PMID 22104207, 2011). "Observing that a specific IL-33 polymorphism, SNP (single nucleotide polymorphism) rs1929992, has been associated with susceptibility to various autoimmune diseases, raises the critical question of whether this SNP also impacts susceptibility to CSU." (PMID 39769469, 2024). "For example, it has been noted that elevated levels of serum IL-33 and IL-33 receptor genetic polymorphism are evident in patients with multiple sclerosis, suggesting a significant role of this cytokine in the pathogenesis of autoimmune disorders." (PMID 38731070, 2024). "Given the grounding of autoimmunity in the etiopathogenesis of CSU and its association with various autoimmune diseases as reported in the literature, our research investigated how IL-33, a molecule common to both CSU and autoimmune diseases, has been genetically approached in previous studies." (PMID 39769469, 2024). "Interleukin-33 (IL-33) is a cytokine associated with inflammatory and autoimmune diseases." (PMID 35371856, 2022).
autoimmune disease (continued). "In recent years, IL-33 has been linked to several different autoimmune diseases." (PMID 30574145, 2018). "Decreased 1,25-dihydroxycholecalciferol [1,25(OH)2D] and upregulated IL-33/IL-31 axis can alter the balance between inflammatory Th1/Th17 cells and T regulatory (Treg) cells and promote the bacterial translocation, associated with the pathophysiological processes of autoimmune diseases like IBD." (PMID 39758314, 2024). "Interleukin-33 (IL-33), encoded by the IL-33 gene, functions as a unique cytokine that may induce severe pathological changes and potentially lead to chronic inflammation, cancer, Behçet's disease, and autoimmune disease." (PMID 30984790, 2019). "Local IL-33 blockade via delivery of a decoy receptor improves outcomes, highlighting tissue factors as druggable targets for chronic CNS autoimmune disorders." (PMID 40227193, 2025). "Earlier studies on IL-33 primarily focused on allergic reactions, inflammation, infections, autoimmune diseases, heart and lung diseases, among others." (PMID 41272907, 2025). "The robust production of type 1 interferon (IFN-I) and IL-33 is well-known in autoimmune disorders, including SLE and psoriasis." (PMID 39751976, 2025). "This versatility likely underlies the dual role of the IL-33/ST2 signaling pathway in various diseases, such as those affecting the central nervous system, cancer, fibrosis, autoimmune disorders, and inflammatory conditions." (PMID 39925809, 2025). "IL-33, a member of the IL-1 family, modulates the Th2 immune response and serves as an important immunomodulator in allergic, infectious, or autoimmune diseases." (PMID 40142865, 2025). "IL1a and IL33 are both IL-1 family proteins, both having broad expression patterns and pleiotropic, inflammatory effects, and contribute to inflammatory and autoimmune disorders." (PMID 41155532, 2025). "More recently, the possible role of IL-33, a member of the IL-1 cytokine family, was described in RA and other autoimmune diseases." (PMID 39519235, 2024). "IL33 is a cytokine belonging to the interleukin family and plays complicated roles in the pathogenesis of autoimmune diseases and tumors." (PMID 36567723, 2022). "A study has reported that the organism can release intracellular IL-33 under stress and infection, which plays an important role in an allergic reaction, inflammation, autoimmune disease, and host defense." (PMID 35096114, 2022). "Inhibition of IL-33 leads to a marked improvement in inflammatory pathology, demonstrating the importance of this cytokine in autoimmune diseases." (PMID 36362030, 2022). "Herein, we summarize our current understanding of the biological functions of IL-33 and its roles in the pathogenesis of various conditions, including inflammatory and autoimmune diseases, infections, cancers, and cases of organ transplantation." (PMID 36291105, 2022). "In some autoimmune diseases such as psoriasis, elevated levels of IL-33 produced by MCs can occur in the psoriatic scabs of the skin with mediation of the inflammatory process." (PMID 36362030, 2022). "IL-33 can also be released after stress and infection, which plays an important role in an allergic reaction, inflammation, autoimmune disease, and host defense." (PMID 35096114, 2022). "Interleukin-33 (IL-33), a member of the IL-1 family, is a multifunctional cytokine that participates in various inflammatory and autoimmune diseases with pathological or protectives roles." (PMID 33621202, 2021). "IL1RL1 activates the MyD88/NF-κB signaling pathway to promote the suppressive effect of Tregs in inflammatory diseases, but the role of IL-33 in autoimmune diseases and tumors is controversial." (PMID 34012433, 2021). "The pleiotropic character of IL-33 indicates its potential as an essential player in the pathogenesis of autoimmune diseases." (PMID 34177886, 2021).
autoimmune disease (continued). "An increasing body of evidence also implies a crucial role of IL-33 in the pathogenesis of autoimmune disorders, such as inflammatory bowel disease, multiple sclerosis, psoriasis, and diabetes." (PMID 34177886, 2021). "Several authors including us have shown that the administration of IL-33 had a significant effect on the increased regulatory FoxP3+ cells, which suppress autoimmune diseases including the MLD–STZ diabetes." (PMID 34803672, 2021). "With low dose and mutein IL-2 therapy currently advancing through clinical trials as a method for in vivo Treg expansion in autoimmune diseases and transplantation, there is now an attractive argument for exploring IL-33 therapy for the same indications." (PMID 33314772, 2021). "Activated MCs generate numerous cytokines that mediate autoimmune diseases, including pSS, and stimulate the release of inflammatory autocrine cytokines such as IL-33 and IL-1." (PMID 32560266, 2020). "When the production of IL-33 exceeds certain limits, there is an increase in systemic inflammation with worsening and exacerbation of autoimmune disorders." (PMID 32560266, 2020). "The IL-33/ST2 axis is crucial in experimental models of autoimmune diseases as ST2 deletion improves the development of T-cell-mediated disease." (PMID 32560266, 2020). "Interleukin-33 (IL-33) is a member of the IL-1 cytokine superfamily, and plays an important role in innate immunity, inflammatory and autoimmune diseases." (PMID 32363166, 2020). "In an interesting article, it was reported that IL-33 is increased in autoimmune diseases, including pSS." (PMID 32560266, 2020). "IL-33 as an alarmin was widely discussed about its functions in several different types of autoimmune diseases." (PMID 32676507, 2020). "Conflicting actions of IL-33 have also been described in other models of autoimmune diseases, such as experimental autoimmune encephalomyelitis (EAE)." (PMID 33182616, 2020). "IL-33 was shown to play important roles in either driving or dampening dysregulated T cells responses in autoimmune diseases." (PMID 30949175, 2019). "In this review, we discuss some of the latest discoveries regarding IL-31 and IL-33 among allergic and autoimmune diseases." (PMID 31766607, 2019). "Interleukin-33 (IL-33) represents a recently discovered cytokine belonging to the IL-1 family, and plays a major role in inflammatory, infectious, and autoimmune diseases." (PMID 30769901, 2019). "To summarize, our review shows that the IL-31/IL-33 axis represents a potential pathway of inflammation in allergic and autoimmune diseases." (PMID 31766607, 2019). "Interleukin-33 (IL-33) is a cytokine belonging to the IL-1 family, playing a role in inflammatory, infectious and autoimmune diseases and expressed in the cellular nucleus in several tissues." (PMID 30769901, 2019). "On the other hand, IL-33 was found to be involved in the progression of many chronic inflammatory and autoimmune diseases." (PMID 29713240, 2018). "Dysregulated macrophage responses were shown to contribute to many autoimmune diseases pathogenesis by the production of proinflammatory cytokines such as IL-33, ST2, and IL-1β, as well as proinflammatory chemokine (MCP-1)." (PMID 29713240, 2018). "Our results were consistent with previous studies that showed elevated serum IL-33 in autoimmune diseases." (PMID 26675669, 2015). "It has been proven that IL-33 and its receptor play an important role in inflammation, infection, and autoimmune diseases." (PMID 25032216, 2014). "Th17 cells that support autoimmune disease are characterized by increased expression of cytokines including IL-33, surface markers including IL-23R and transcription factors including T-bet." (PMID 23844143, 2013). "IL-33/ST2 signaling can promote cell-dependent inflammatory responses and may have opposite effects in inflammatory or allergic conditions or diseases (such as cancer and autoimmune diseases), reflecting the duality of action of the IL-33/ST2 pathway." (PMID 39925809, 2025).